LGALS3 (galectin 3)
Diseases named in the same sentence as LGALS3 in open-access papers (continued):
Sharing a sentence is not in itself a finding about the gene and the disease.
heart failure (continued). "Biomarkers related to fibrosis, such as N-terminal propeptide of type I and III procollagens (PINP and PIIINP, respectively), galectin-3 (gal-3), and soluble ST2 protein (ST2) have been associated with poor outcome among heart failure patients." (PMID 26217237, 2015). "Galectin-3 is a ß-galactoside-binding lectin expressed in most of tissues in normal conditions and overexpressed in myocardium from early stages of heart failure (HF)." (PMID 26116131, 2014). "In the clinical setting galectin-3 levels have been shown to correlate with clinical outcomes in patients with heart failure, providing incremental prognostic value to NT-proBNP." (PMID 24156746, 2013). "In the last years, galectin 3 has emerged as an important mediator of cardiac remodeling in heart failure through its ability to stimulate fibrosis, although its specific role and the factors involved in its stimulation are under discussion." (PMID 22844495, 2012). "A recent study, supporting its profibrotic role, has established a relationship between serum galectin 3 and serum markers of cardiac extracellular matrix turnover in heart failure patients." (PMID 22844495, 2012). "Galectin-3 is an emerging biomarker which has been studied in relatively small heart failure (HF) cohorts with predominantly systolic HF." (PMID 21189092, 2011). "The predictive power of plasma galectin-3 appears to be predominantly strong in heart failure patients with preserved left ventricular ejection fraction." (PMID 21189092, 2011). "Galectin-3 (Gal-3) regulates inflammation and myocardial remodeling and predicts adverse outcomes in myocardial infarction and heart failure, yet its role in catecholamine-driven stress cardiomyopathy, including TS, remains unclear." (PMID 41957708, 2026). "So, in the 2013 study, researchers found that galectin-3 plays a significant role in myocardial fibrosis, which determines the transition from compensated to decompensated heart failure, thus highlighting the clinical importance of the correlation between galectin-3 and HFpEF development." (PMID 40076723, 2025). "Galectin-3 is another novel biomarker of inflammation and fibrosis in the cardiovascular and renal systems that has freshly emerged as a predictor of cardiovascular disease and heart failure." (PMID 40283065, 2025). "In addition, galectin-3 has been identified as a marker of cardiac remodeling and progression to heart failure in various clinical settings, further reinforcing its diagnostic and therapeutic relevance in chronic ischemic conditions." (PMID 40430046, 2025). "Moreover, data from the HF-ACTION study revealed that galectin-3 levels in ambulatory heart failure patients were predictive of long-term outcomes, reinforcing its utility as a biomarker for heart failure management." (PMID 39063659, 2024). "Based on a large number of in vitro studies, galectin-3 had been identified as an important fibrogenic protein, and in vivo studies had also proved that this fibrogenic effect of gal-3 may be closely related to the prognosis of heart failure." (PMID 38680895, 2024). "Biomarkers like FGF-21 and galectin-3 could provide greater insight into heart failure severity, especially in diabetic patients." (PMID 39597026, 2024). "In addition, there are studies suggesting that galectin 3 plays a central role in heart failure pathophysiology through myocardial inflammation and fibrosis, thus becoming a predictor of heart failure." (PMID 38535084, 2024). "Accumulating evidence points toward the pathogenetic role of galectin-3 in heart failure, as its expression in myofibroblasts may induce the production and deposition of type 1 collagen, promoting cardiac remodeling and myocardial fibrosis." (PMID 38519721, 2024).
heart failure (continued). "In detail, a recent review states that serial monitoring of N-terminal pro-B-type natriuretic peptide (NT-proBNP), cardiac troponins (cTn), soluble suppression of tumorigenesis-2 (sST2), and galectin-3 levels can help predict clinical outcomes in patients with heart failure." (PMID 38397422, 2024). "Galectin-3 (Gal-3) is a lectin that binds to β-galactoside, which is considered a pivotal connector among inflammation, fibrosis, and detrimental cardiac remodeling in heart failure." (PMID 39335666, 2024). "Moreover, in individuals with ST-segment elevation myocardial infarction, elevated galectin-3 levels were predictive of post-infarction heart failure development, emphasizing its role in adverse cardiac remodeling and the progression of diastolic dysfunction." (PMID 39063659, 2024). "Overall, while galectin-3 is a promising biomarker in both HFrEF and HFpEF, its role and therapeutic implications differ, warranting tailored approaches to management in these distinct heart failure phenotypes." (PMID 39063659, 2024). "Furthermore, galectin-3 levels correlate with disease severity and prognosis in heart failure and atrial fibrillation, offering valuable insights for risk stratification and treatment decision making." (PMID 39063659, 2024). "Its reported link to heart failure, myocardial infarction, and ventricular arrhythmias, wherein elevated levels of galectin-3 correlate with adverse cardiac remodeling and reduced ejection fraction, makes it a potential biomarker for cardiac risk stratification." (PMID 39338248, 2024). "Van Kimmenade and colleagues demonstrated a correlation between galectin-3 and heart failure." (PMID 37513890, 2023). "Second, whether good control of plasma galectin-3 levels resulting from medication such as SGLT2 or ARNI in patients with heart failure with a preserved ejection fraction further enhances the survival prognosis in this group of patients is still unknown." (PMID 36673621, 2023). "The question arises whether an increase in galectin-3 results from heart failure or results in heart failure." (PMID 37513890, 2023). "Although our study showed that the use of spironolactone at a dose of 50 mg per day provided a greater reduction in galectin-3 concentration than a dose of 25 mg in patients with heart failure with a reduced ejection fraction, certain limitations were present in our study." (PMID 36673621, 2023). "Moreover, in patients with heart failure, especially heart failure with a reduced ejection fraction, the reduction in galectin-3 concentrations achieved through treatment with spironolactone showed a significant improvement in cardiac function." (PMID 36673621, 2023). "Interestingly, despite the fact that heart failure was more common in our control group and that galectin-3 is known as a marker for heart failure, its levels were even higher in the COVID-19 group that had a lower prevalence of heart failure." (PMID 37175392, 2023). "Serum biomarkers such as Galectin-3 or N-terminal prohormone B-type natriuretic peptide (NT-proBNP) are involved in remodeling and heart failure (HF) development and could support the diagnosis of AS." (PMID 37109323, 2023). "In fact, galectin-3 expression appears to begin prior to the onset of heart failure." (PMID 37715793, 2023). "According to the NYHA functional classification, we discovered a noticeable decrease in the mean concentration of galectin-3 in class III heart failure, from 63.04 ± 20.79 to 50.76 ± 18.70 (p < 0.001) and lowered the most in the NYHA IV group, however, p = 0.05 due to the small sample size." (PMID 36673621, 2023). "The trials show galectin-3 as a biomarker of prognostic importance, being a significant predictor of mortality and rehospitalization in the population with acute, as well as chronic, heart failure." (PMID 35410028, 2022).
heart failure (continued). "Moreover, galectin-3 levels correlated positively with the severity of circulatory system insufficiency expressed using the Ross Heart Failure Scale, and was lower in children treated with oral spironolactone than in those without." (PMID 35410028, 2022). "The role of galectin-3 is widely investigated in adults with heart failure." (PMID 35410028, 2022). "Galectin-3, which is involved in myocardial remodeling and fibrosis, can also be detected in urine and has been shown as a good prognostic factor in patients with heart failure with preserved ejection fraction." (PMID 35626917, 2022). "As studied in adults, galectin-3 may be useful for predicting the future development of new onset of heart failure and for follow up not only as a single factor, but mainly in combination with other proteins." (PMID 35410028, 2022). "In addition, galectin-3 is considered an active contributor to the development of heart failure as mediator of the myocardial fibrosis." (PMID 35042522, 2022). "Besides the already clinically established biomarkers for heart failure like the brain natriuretic peptides, galectin-3 was identified to correlate with a reduced cardiac function." (PMID 34561496, 2021). "Thus far, our study is the only HFpEF focused study that has looked at the ability of Galectin-3 over two time points to predict future heart failure development in an asymptomatic population." (PMID 33563287, 2021). "As expected, higher galectin-3 levels were related to higher prevalence of heart failure." (PMID 34561496, 2021). "Of interest, the findings of the present study indicate a strong influence of cardiovascular risk factors on the prospective association between galectin-3 and diastolic dysfunction in T2DM, whereas comorbidities and heart failure medication intake seem to have a lower impact than CVRF." (PMID 34561496, 2021). "In this review, we address the similarities and differences between galectin-3 and sST2 for prognostic prediction in adults and children with heart failure requiring extracorporeal life support and highlight the significant lack of progress in pediatric biomarker discovery and utilization." (PMID 33513858, 2021). "A long-term follow-up study showed a significant increase in the rate of new-set heart failure with increased galectin-3 concentrations, Another spanning 10 years study also found that dynamically elevated galectin-3 level was more closely associated with new-set heart failure and mortality." (PMID 35141299, 2021). "The role of Galectin-3 in the development and progression of heart failure has been reported." (PMID 33686023, 2021). "Galectin-3 is an initiator of the inflammation process in heart failure." (PMID 33513858, 2021). "Hence, galectin-3 in general seems to be inferior to the established biomarker NT-proBNP in assessing and monitoring heart failure." (PMID 34561496, 2021). "Galectin-3 and heart failure: prognosis, prediction & clinical utility." (PMID 33656072, 2021). "The 2013 US guidelines have recommended galectin-3 using for heart failure risk stratification, although it has not been used clinically." (PMID 35141299, 2021). "Although the predictive value of galectin-3 for heart failure with preserved ejection fraction has been demonstrated, the diagnostic value remains unclear." (PMID 35141299, 2021). "Therefore, galectin-3 has been identified as a prognostic factor for heart failure, especially HFpEF." (PMID 35141299, 2021). "They considered that the cardiac structural changes - in the form of inflammation & fibrosis - and the clinical worsening correlations with galectin-3 level were considered as an indirect supporting evidence of a significant action of galectin-3 in the substantial pathogenesis of heart failure." (PMID 33248453, 2020).
heart failure (continued). "Galectin-3 was also the only biomarker associated with the development of acute ischemic events and heart failure or death in T2DM patients, while, in nondiabetics, MCP-1 and NT-proBNP, respectively, were related to these events." (PMID 32294902, 2020). "Galectin-3 has also been shown to be an excellent predictor of mortality in heart failure patients." (PMID 33195327, 2020). "This can be interpreted by the fact that apoptosis is concerned in the transition to decompensated HF, and since galectin-3 is entangled in apoptosis; thus, the increase in galectin-3 levels is may be prompted to heart failure decompensation." (PMID 33248453, 2020). "Plasma galectin- 3 (Gal-3), a member of the carbohydrate-binding protein family of lectins, is currently being studied as a potential novel biomarker for cardiac fibrosis and adverse remodeling in heart failure." (PMID 32580463, 2020). "In addition, it has been demonstrated that nT1 and ECV correlate with an increase in circulating SSc activity markers (growth differential factor 15) and predictor of heart failure development (Galectin-3)." (PMID 33351821, 2020). "Galectin-3 (Gal-3) is involved in fibrosis and heart failure." (PMID 31772609, 2019). "We observed galectin-3 positive cells infiltration in this second heart failure model." (PMID 30673749, 2019). "In chronic heart failure, galectin-3 has been demonstrated to be involved in several pathophysiological processes, including myocardial inflammation and fibrosis, which are both pivotal mechanisms of heart failure development and progression." (PMID 31885743, 2019). "We conducted additional experiments to confirm whether the present finding of galectin-3 expression is unique to patients with viral myocarditis or common to other kind of heart failure." (PMID 30673749, 2019). "Recently, serum galectin-3 has been shown to have prognostic value as a biomarker in heart failure." (PMID 30673749, 2019). "The role of galectin-3 has mainly been investigated in adult patients with heart failure." (PMID 29327139, 2018). "We found that galectin-3 and MMP-2 were significantly associated with global cardiac fibrosis, even after adjusting for confounding risk factors, whereas TIMP2 and NT-proBNP were significantly associated with the aggravation of heart failure symptoms." (PMID 30413105, 2018). "We sought to find whether galectin-3 has a prognostic value in patients with heart failure and a reduced left ventricular ejection fraction undergoing ablation of persistent atrial fibrillation." (PMID 30067817, 2018). "Galectin-3 (Gal-3) is a highly versatile lectin involved in several physiological and pathological processes including inflammation and fibrosis, which are pivotal events in development and progression of adverse cardiac remodelling and heart failure (HF)." (PMID 29180917, 2017). "Similarly, galectin-3, another biomarker that has been studied in the field of heart failure, was shown to have a prognostic value for heart in Caucasians, but not in an afro-descendent population." (PMID 29232393, 2017). "The link between renal insufficiency, heart failure and galectin-3 is not completely understood." (PMID 27089335, 2016). "Impaired renal handling of galectin-3 in such patients may explain the relationship between renal function and galectin-3, and may account for the elevated plasma galectin-3 in heart failure." (PMID 27089335, 2016). "Numerous experimental studies have demonstrated recently that galectin-3 might contribute to the pathophysiology of an adverse structural remodeling within the development of heart failure." (PMID 28044067, 2016). "Heart failure is accompanied by abnormalities in ventricular-vascularinteraction due to increased myocardial and arterial stiffness.Galectin-3 is a recently discovered biomarker that plays an importantrole in myocardial and vascular fibrosis and heart failureprogression." (PMID 26760784, 2016).
heart failure (continued). "Nevertheless galectin-3, and specifically increases in galectin-3, were independent of treatment and NT-proBNP associated with all-cause mortality or heart failure rehospitalisation." (PMID 26942916, 2016). "The present clinical finding might be supported by the mentioned experimental data, indicating that galectin-3 is already increased at early heart failure stages with beginning cardiac hypertrophy." (PMID 28044067, 2016). "The aim of this study was to determine whether galectin-3 is correlatedwith arterial stiffening markers and impaired ventricular-arterialcoupling in decompensated heart failure patients." (PMID 26760784, 2016). "Moreover, we also showed that PKC-α promotes cardiac fibrosis and heart failure by stimulation of galectin-3 expression." (PMID 28066244, 2016). "Targeting Galectin-3 may be an upstream therapeutic option for the treatment of all types of heart failure." (PMID 26582585, 2015). "Fourth, no other markers (eg, galectin-3, high sensitivity troponins, growth differentiation factor 15) that have been suggested to be associated with risks of heart failure were available for all patients." (PMID 25347817, 2014). "Galectin-3 has been shown to play a role in inflammatory diseases, cancer and heart failure." (PMID 23056639, 2012). "Plasma galectin-3 is an independent predictor of outcome in large cohort of heart failure patients." (PMID 21189092, 2011). "Primary outcome: death or admission for heart failure: doubling of galectin-3." (PMID 21189092, 2011). "The study indicates that effective LA reverse remodeling, associated with lower galectin-3 levels, could improve clinical outcomes in patients with dilated cardiomyopathy, underscoring the importance of galectin-3 as a biomarker for therapeutic strategies and prognosis in heart failure management." (PMID 39063659, 2024). "Therefore, it has not been demonstrated whether long-term management of plasma galectin-3 improves mortality and hospitalization in heart failure patients, especially in those with a reduced ejection fraction." (PMID 36673621, 2023). "Furthermore, spironolactone has the ability to control galectin-3 levels in heart failure patients." (PMID 36673621, 2023). "Thus, we posed the intriguing question concerning whether there is a distinction between galectin-3, insulin resistance, and subgroups of patients with heart failure." (PMID 36673621, 2023). "Galectin-3 itself has been shown to be a novel inflammatory biomarker, which raises an intriguing question as to whether inflammation in patients without heart failure or hemodynamic disturbances is associated with increased NT-proBNP and galectin-3 or not." (PMID 36673621, 2023). "Moreover, galectin 3 affects fibrosis of many other organs, including the heart after myocardial infarction (MI), hence the need to lower the level of this glycoprotein in order to avoid heart failure after MI." (PMID 35742776, 2022). "In summation, galectin-3 could be a valuable prognostic biomarker in the assessment of heart failure in children; however, the data are still sparse and further trials are necessary to evaluate the value of the biomarker and its relationship to hemodynamical dysfunction." (PMID 35410028, 2022). "● miR-21 could provide a diagnosis of early heart failure; ● miR-21 was increased and related to NT-proBNP and galectin-3 levels in acute HF combined with DM; ● miR-21 increased in response to an acute exhaustive exercise in CHF (chronic heart failure) patients." (PMID 36304546, 2022). "Another study found that galectin-3 could be used as a biomarker to assess heart failure patients." (PMID 33686023, 2021). "Targeting galectin-3 may be a potential therapy to improve the outcomes of heart failure." (PMID 33513858, 2021). "Thus, galectin-3 may be a novel candidate biomarker for the diagnosis, analysis and prognosis of various cardiac diseases, including heart failure." (PMID 32899694, 2020).